IL1B (interleukin 1 beta)
Diseases named in the same sentence as IL1B in open-access papers (continued):
Sharing a sentence is not in itself a finding about the gene and the disease.
tumor (continued). "High levels of pro-inflammatory factors in the microenvironment of the tumour, such as GM-CSF, IL-1b, IL-6, and S-100, induce the recruitment and expansion of myeloid-derived suppressor cells, increasing pro-tumour activity." (PMID 26913068, 2016). "While naive mice from both groups had similar and very low levels of IL-1β in lung tissues, tumor-bearing WT mice had increased levels of IL-1β protein in the lung." (PMID 27786298, 2016). "Inhibition of IL-1β secretion by GSTO1 inhibitors also has exciting implications on tumour progression and tumour-immune cell crosstalk in the microenvironment." (PMID 27703239, 2016). "Activation of Cysteine-rich 61 protein (CCN1) also inhibited the oncolytic virus anti-tumor efficacy in glioblastoma through activation and infiltration of inflammatory TAMs and NK cells expressing IL-1β, IFNγ, CXCL10, and MCP-1/3." (PMID 28536380, 2016). "It is likely that IL-1B directly impacts on tumour aggressiveness and metastatic potential due to its ability to influence multiple molecular pathways, and that blocking IL-1B activity therefore has the potential to be an effective anti-cancer therapy." (PMID 27765923, 2016). "The modified Miles assay revealed that Piezo2 knockdown decreased VEGF- and IL-1β-mediated vascular leak, suggesting that Piezo2 plays an anti-permeability role during tumor angiogenesis." (PMID 27329839, 2016). "The central players involved in inflammation-mediated tumor progression include IL-1β, IL-6 and TNF-α." (PMID 26896068, 2016). "We verified the efficacy of anti-IL-1R1 in vivo by measuring the relative expression of IL-1-responsive genes and saw a significant reduction in the expression of Il6, Il1b and Ptgs2 in tumours from anti-IL-1R1-treated mice relative to IgG-treated mice." (PMID 27708283, 2016). "IL-1β is a pleiotropic proinflammatory cytokine and can be secreted by immune, stromal, and tumor cells." (PMID 27057094, 2016). "Our results have demonstrated that inflammasome and IL-1β play a critical role in promoting tumor growth and metastasis." (PMID 27786298, 2016). "Inflammatory cytokines, such as tumor necrosis factor (TNF)-α, interleukin (IL)-1β and IL-6, produced by a tumor and/or activated by immune cells, have been shown to stimulate cancer cell growth and influence clinical disease status and prognosis." (PMID 26959121, 2016). "Expression of IL-1β mRNA was elevated in the brain of all tumor-bearing mice but was highest in mice injected with aliquot β (p < 0.05)." (PMID 25709898, 2015). "We also observed that cancer cell expression of CDH1/IL-1β is predictive for the presence of significant biological effects of hMSCs on tumor cells." (PMID 26204886, 2015). "The function of ATP is to recruit monocytes and macrophages to the dying tumor cells and stimulate secretion of IL-1β, a key cytokine to polarize interferon-gamma-producing CD8+ T cells." (PMID 25544770, 2015). "IL-1β induces IL-6 synthesis and release by T-lymphocytes, contributing to proinflammatory polarization of the tumor microenvironment a." (PMID 26131447, 2015). "Elevation of serum IL-6 and IL-1β in tumor-bearing mice after docetaxel treatment implicates that docetaxel gives rise to side effects." (PMID 25797259, 2015). "In HT-29 cells either tumor and healthy colon tissue derived DNA significantly affected the expression of IL-1β gene related to PBS treated controls." (PMID 26133168, 2015). "Both NF-κB and STAT3 mediated signals derived from tumor cells or infiltrating immune cells such as IL-1β, TNF-α, ROS or TLRs play a key role in the inflammatory activation of stromal fibroblasts associated to pathologies such as RA and cancer." (PMID 26501341, 2015). "We also evaluated the IFN-γ and IL-1β production in tumor masses and spleens at different times in both STM-treated and untreated groups." (PMID 26158862, 2015).
tumor (continued). "Since IL-1β is a key cytokine involved in ICD-induced anti-tumor responses, IL-1β-producing DCs would be, in turn, able to initiate an anti-tumor immune response directed toward living cancer cells." (PMID 26217341, 2015). "This, in turn, activates transcription of pro-inflammatory factors including COX-2, IL-6, IL-1β, and TNFα, which promote tumor growth and progression through various mechanisms." (PMID 26107623, 2015). "Different from IGF1, IL-1β is a very classical NF-κB activating cytokine, which is frequently found in the tumor environment." (PMID 26318844, 2015). "Although IL-1β has been known to activate NF-κB signaling in MDSCs to affect tumor progression, IL-1β has recently been reported to influence B16 tumor progression via STAT1 signaling." (PMID 25706411, 2015). "The present study contributes to further clarifying the intricate mechanism by which IL-1β subverts the tumor stroma into a pro-tumor environment." (PMID 26327350, 2015). "Sarcomas growing in Ptx3−/− host showed a much higher macrophage and neutrophil infiltrate, and higher levels of CCL2, CXCL2, TNFα, IL-6, IL-1β, and VEGF, suggesting an exacerbated tumor-associated inflammatory response." (PMID 26075183, 2015). "CCL3, CCL4, and IL-1β expression was higher in the adipose tissue and tumor tissue in the cachectic group." (PMID 26732354, 2015). "Cytokines such as, IL-6, TNF-α and IL-1β have been shown to be able to increase tumor cell pro-coagulant activity, enhancing clotting activation in cancer patients." (PMID 26192925, 2015). "The downside of this is more production of pro-inflammatory cytokines, especially IL-1β and related cytokines with a tumor growth promotion effect." (PMID 26689911, 2015). "The tumor cell survival is dependent of growth factors, like TNFα, IL1β, IL6 and VEGFα secreted by mast cells, macrophages and MDSCs." (PMID 25747113, 2015). "Because IL-8 is a chemokine that promotes tumor angiogenesis, we further analyzed the levels of secreted IL-8 protein in MSCs treated with recombinant IL-1β (30 ng/mL) and TNF-α (20 ng/mL) using ELISA." (PMID 26517517, 2015). "Second, in contrast to cultured cells in vitro, TQ induced tumor NF-κB reporter activity and mRNA levels of the key NF-κB targets, IL-1β and TNF-α, in drug-treated mice." (PMID 26215403, 2015). "The secretion of cytokines such as IL-1β and TNFα in the irradiated tumor microenvironment, can affect macrophage function and phenotype." (PMID 26348470, 2015). "The levels of serum IL-6 and IL-1β in tumor bearing mice slightly increased after the docetaxel treatment, suggesting that docetaxel exacerbates these side effects." (PMID 25797259, 2015). "TNF-α, IL-1β and IL-6 play important roles in the tumor microenvironment and contribute to the promotion of inflammation associated carcinogenesis." (PMID 25763529, 2015). "In situ hybridization showed increased expression of this miRNA in tumor astrocytes and colocalization with IL-1β was observed." (PMID 25986346, 2015). "For example, IL-1β induces secretion of chemokines by both tumor and tumor-microenvironmental cells and thus promotes cancer invasiveness." (PMID 24734023, 2014). "Haptenation will also cause keratinocytes to release IL-1β, IL-6, IL-18, and TNFα, which have been shown to cause MDSC recruitment and infiltration at the tumor site, subsequently causing IL-10 release and immune suppression." (PMID 24949488, 2014). "In tumor cells, IL-1β induces the secretion of growth- and invasion-promoting factors, matrix-metalloproteases and angiogenic molecules, including VEGF-A and basic fibroblast growth factor." (PMID 25120672, 2014). "In the present study, upon contact with tumor cells, macrophages were found to express a higher level of VEGF-C which was associated with an increase in the expression of IL-1β and TNF-α and their receptors." (PMID 25120672, 2014). "In various tumor models, we found that IL-1β induces increased tumor growth, invasiveness, and angiogenesis, when compared to IL-1α." (PMID 24734023, 2014).
tumor (continued). "Tumour associated macrophages or myeloid-derived suppressive cells, CD4+ Foxp3+ Treg cells and Th17 cells and their associated cytokines Il-6, TNF, IL-1β, IL-23 and TGF-β are generally recognized as dominant tumour-promoting forces." (PMID 24963981, 2014). "IL-1β is only active in its secreted form and mediates inflammation, which promotes carcinogenesis, tumor invasiveness and immunosuppression." (PMID 24571667, 2014). "Interleukin (IL)-1 signaling through its agonistic proteins IL-1α and IL-1β is involved in inflammatory responses, but also affects malignant processes including tumorigenesis, tumor invasiveness, and tumor-host interactions." (PMID 24901233, 2014). "Similar observations were described in other experimental systems using IL-1β-transfected tumor cells." (PMID 24734023, 2014). "Gelatinase B/MMP-9 is considered to be a tuner and amplifier of inflammatory and immune functions and is up regulated by pro-inflammatory cytokines such as TNFα, IL-1β, IL-6 and TGFβ in a wide variety of human tumour cells, stromal and endothelial cells." (PMID 24473089, 2014). "Th17 development was shown to be dependent on IL-1b/IL-6/IL-23 and NO production by MDSCs in both tumor-bearing mice and cancer patients." (PMID 25538892, 2014). "While IL-1α and IL-1β can have similar biological activities in recombinant or secreted form, these closely related cytokines seem to play very different roles in tumor immunology." (PMID 24416335, 2014). "For example, chronic overactivation of the IL-1β system has been considered a tumor promoting condition, arguing in favor of IL-1β inhibition for tumor prevention or therapy." (PMID 25054228, 2014). "Perhaps, TNF-α had a protector role in this SCC model, since this cytokine also have been described as involved with anti-tumor immune response in the presence of IL-1β." (PMID 25268644, 2014). "Results of our studies have shown that IL-1β is a major mediator in the tumor microenvironment, which plays a crucial role in the angiogenic response." (PMID 24734023, 2014). "Using IL-1 KO mice, we demonstrated that microenvironment-derived IL-1β, and to a much lesser extent IL-1α, is responsible for in vivo tumor angiogenesis and invasiveness of B16 melanoma cells." (PMID 24734023, 2014). "In our studies, we found that blocking a major, alarm, pro-inflammatory molecule derived from myeloid cells, i.e., IL-1β can lead to a significant amelioration of tumor angiogenesis." (PMID 24734023, 2014). "IL-1β of host- or tumor cell-origin is also essential for the invasiveness of existing malignant cells and for promoting angiogenesis, and the elevated expression of IL-1β is a poor prognostic factor." (PMID 28548063, 2014). "ATP release will induce P2RX7, which will cause the activation of NLRP3 on dermal APCs, eliciting the production of IL-1β and IL-18 which has been shown to decrease the tumor responsiveness to certain vaccinations." (PMID 24949488, 2014). "IL-1β neutralization largely inhibited infiltration of myeloid cells, which are obligatory for tumor-mediated angiogenesis." (PMID 24734023, 2014). "Anakinra, a competitive inhibitor of IL-1, blocked MPL-pSi induced secretion of IL-1β, and reduced the anti-tumor properties of the microparticles." (PMID 24736547, 2014). "Along the same line, some tumor cytokines, including Interleukin-1 beta, tumor necrosis factor-alpha and interleukin-6, were found to be elevated in HCC patients, have been reported to block IGF-1 production in the liver." (PMID 24586785, 2014). "This secreted IL-1β became increasingly autonomous with later stage disease, implicating it as an evolutionarily advantageous trait for the developing tumor." (PMID 24795727, 2014). "They showed that tumor cell- or host-derived IL-1β promoted tumor initiation, invasiveness, immunosuppression and angiogenesis while IL-1α preferentially activated anti-tumor cell immunity." (PMID 24924428, 2014).
tumor (continued). "IL-1β has many pleiotropic effects involved in inflammation, immunosuppression, cell proliferation and differentiation, tissue regeneration, tumor-promotion, and chemoresistance." (PMID 24795727, 2014). "Angiogenic VEGF-A and lymphangiogenic VEGF-C and VEGF-D were up-regulated in the tumor stromal macrophages of highly metastatic tumors expressing IL-1α and/or IL-1β." (PMID 24924428, 2014). "In a tumour milieu LCN2 is potentiated by proinflammatory cytokines Il-1β, TNF-α, and IL-17 and is involved in the epithelial to mesenchymal transition (EMT)." (PMID 25010215, 2014). "Dumont and colleagues have demonstrated that the supernatant from M1 polarized macrophages, which produce TNF-α, IL-1β and ROS, can induce tumor cell growth inhibition in vitro, and in gal-3 knockdown cells, it can increase cell death susceptibility." (PMID 25369297, 2014). "Both HNSCC derived cell lines and invasive HNSCC tumor cells produce proinflammatory cytokines including IL-1β, TNF-α, and IL-6." (PMID 24465623, 2014). "Impaired tumorigenicity was described for 3-methylcholanthrene-induced tumors in IL-1β KO mice, whereas most rapid tumor development and inflammation was demonstrated in IL-1Ra KO mice." (PMID 24901233, 2014). "Overexpression of IL-1β within the tumor microenvironment potentiates carcinogenesis due to local inflammatory responses that possibly contribute to an increased rate of tumor development." (PMID 28548063, 2014). "Once at the tumor site, IL-17 induced production of IL-1β and IL-23 in MDSC, which amplify differentiation of γδ17 cells." (PMID 25505472, 2014). "A high dose of TNF-α and IL-1β was found to induce tumor cell cytotoxicity and reduce tumor cell resistance to the apoptotic agent H2O2, in a synergistic manner." (PMID 25120672, 2014). "Significant (P < 0.01) decreases of the splenic TNF-α, IL-1β and IL-10 contents were observed in tumor-bearing control mice as compared with intact control mice, respectively." (PMID 25477992, 2014). "In tumor tissue, Myc gene, an oncogene is activated and triggers the expression and release of the inflammatory cytokine, IL-1β." (PMID 24454803, 2014). "IL-1β inhibition also reduced in vivo tumor development in mice injected subcutaneously with tumor cells." (PMID 24734023, 2014). "Activated glia can produce multiple cytokines, chemokines,and enzymes that lead to increased tumor invasion, including IL-1β and TNF-α, markers that were upregulatedin this study." (PMID 25129445, 2014). "Voronov and colleagues have reported IL-1α and IL-1β have distinct effects at tumor sites, using genetically engineered cells or mice with distinct patterns of IL-1 expression." (PMID 24924428, 2014). "In IL-1α KO mice, tumor growth and angiogenesis in Matrigel plugs were observed to a lesser extent than in WT mice, but higher than those in IL-1β KO mice." (PMID 24734023, 2014). "That work showed more intensive angiogenesis and tumor growth as well as enhanced macrophage accumulation in the tumor microenvironment of syngeneic mice implanted with LLC/IL-1β cells." (PMID 24924428, 2014). "To investigate the biological significance of EGF-induced IL-1β expression in tumor cells, we focused on drug resistance in cisplatin-induced apoptosis." (PMID 23383347, 2013). "But while MDSC die, they release IL-1β, which induces accumulation of deleterious Th17 cells, promoting later tumor relapse." (PMID 23762310, 2013). "IL-1β promotes invasiveness, including tumor angiogenesis, and also induces immune suppression in the host." (PMID 23704929, 2013). "The difference in the expression of IL1B in the tumour and matched non-tumour samples was calculated and correlated to patient overall survival." (PMID 23867201, 2013). "Very little is known about interactions between IL-1α and IL-1β expressed at tumor sites by either the malignant or microenvironment cells." (PMID 23847618, 2013).
tumor (continued). "In human tumor cell lines grown under normoxic conditions, IL-1β up-regulates the functional HIF-1α protein through a classical inflammatory signaling pathway, involving NF-κB and COX-2, resulting in VEGF secretion by the cancer cells." (PMID 23383347, 2013). "Matrix metalloproteinase-2 (MMP-2) and IL-6 participate in endothelial cell injury and the extravasation of tumor cells, and IL-1β, IL-6, and TGF-β are involved in tumor progression." (PMID 23710200, 2013). "The expression of IL-1β stimulates angiogenesis and facilitates tumor growth and metastasis in human cancer cells." (PMID 23383347, 2013). "Similar effects with increased ability to metastasize has also been described for tumor cells expressing IL-1β." (PMID 23951028, 2013). "The inhibition of inflammasomes or neutralization of their products, mainly IL-1β, and IL-18, has profound effects on carcinogenesis and tumor progression." (PMID 23940760, 2013). "Immunosuppression induced by IL-1β in the tumor microenvironment, mainly through MDSC induction, usually inhibits or masks anti-tumor cell immunity induced by cell-associated IL-1α." (PMID 23847618, 2013). "Similar observations were described in other experimental systems using IL-1β-transfected tumor cells (82, –84)." (PMID 23847618, 2013). "Tumor-promoting inflammation is driven by many factors including the presence of the pro-inflammatory cytokines interleukin (IL)-1β and IL-18." (PMID 24273542, 2013). "Production of IL-1β was substantially reduced in women with LLABCs; 8 fold in good (p = 0.002) and 78 fold in poor clinical responders (p = 0.001) (tumour responses assessed by MRM after 2 cycles of AC)." (PMID 23320561, 2013). "At tumor sites, immunosuppressive effector cells, induced by excessive expression of IL-1β inhibit or mask the induction/function of anti-tumor immunosurveillance induced by tumor cell-derived IL-1α." (PMID 23847618, 2013). "COX-2-expressing macrophages are essential for IL-1β-induced neovascularization and tumor progression." (PMID 23383347, 2013). "Secretable IL-1β, derived from the microenvironment or the malignant cells, activates inflammation that promotes invasiveness and induces tumor-mediated suppression." (PMID 23383347, 2013). "TGF-β1 has been demonstrated to suppress INF-γ production by CD8+ T cells and to promote, in concert with IL-6, IL-1β, and IL-10, Treg generation, and Th17 differentiation, thus favoring tumor growth and progression." (PMID 23533994, 2013). "In such patients, one can envision initial systemic neutralization of IL-1β followed by application of IL-1α expressing tumor cell vaccines." (PMID 23847618, 2013). "For example, IL-1β content correlated with aggressive tumors and modulated the microenvironment to the benefit of tumor growth, invasion, and metastasis by activation of proteolytic enzymes, stroma formation and angiogenesis." (PMID 23383347, 2013). "VMH serotonergic activity was increased in tumor bearing or IL-1β peripherally-treated rats and the local administration of a 5-HT antagonist attenuated hypophagia in these animals." (PMID 24314273, 2013). "Second, IL-1β of tumor cell origin has been shown in other studies to stimulate hematological alterations manifested by extensive accumulation in the spleen of Gr-1+CD11b+ immature myeloid cells that induce tumor-mediated immune suppression." (PMID 24216700, 2013). "This M2-type macrophages are opposed to the “classic” M1-type that are activated by Th1 cytokines (IFN-γ, IL-1β) and are endowed with anti-tumor properties." (PMID 23950747, 2013). "The expression of IL-1α in 3-MCA-induced tumor cells from IL-1β KO mice concomitantly activated a strong T helper and CTL response, which also contributed to the reduced in vivo growth of these cells in WT mice." (PMID 23847618, 2013).